TNF (tumor necrosis factor)
Diseases named in the same sentence as TNF in open-access papers (continued):
Sharing a sentence is not in itself a finding about the gene and the disease.
tumor (continued). "In contrast, as sporadic reports of tumor growth during anti-TNFα mAb use have been published, the possibility that anti-TNFα mAb use may influence tumor growth cannot be ruled out." (PMID 36996146, 2023). "Moreover, single-agent nivolumab and ipilimumab significantly decreased the production of tumour-promoting cytokine TNF-α under neutral pH conditions and acidic conditions." (PMID 35708739, 2023). "However, the precise interactions between AM-secreted TNF-α and the stroma or the tumor cells themselves remain a complex network that warrants further detailed investigation." (PMID 37092550, 2023). "Among them, TNF-α plays a pro-tumor role by promoting DNA damage and inhibiting DNA repair." (PMID 37020871, 2023). "Although named for its antitumor properties, TNFα has tumour-promoting properties." (PMID 36900285, 2023). "Low expression of TNF-α could result in the killing of tumor cells, whereas higher levels could lead to cachexia and inflammation." (PMID 37520246, 2023). "In addition, cytokines (e.g., tumor necrosis factor-α (TNF-α) and interleukin-6 (IL-6)) are released during tumor ICD accompanied by a strong inflammatory response." (PMID 37766117, 2023). "At the same time, TNF can also activate the apoptosis pathway in tumor cells, like FasL." (PMID 37457707, 2023). "Furthermore, these DC/tumor fusion cells produced higher levels of TNF-α, IL-1β and IL-6 than DCs cultured alone or simply mixed with tumor cells." (PMID 37419930, 2023). "Consistent with the enhanced CTL expansion, the proinflammatory cytokines interleukin‐2 (Il‐2), tumor necrosis factor (Tnf)‐α, and interferon (Ifn)‐γ, which promote antitumor immune response, were found significantly enhanced in tumor tissues after G4 treatment." (PMID 37222047, 2023). "TNF-α leads to activation of a JNK signaling pathway that contributes to tumor cell death." (PMID 37514190, 2023). "TNF-α also participates in the development of malignancies as an endogenous tumor-promoting factor." (PMID 37964929, 2023). "Similar to the H358 model, we observed a gradual decrease in macrophage phagocytosis of tumor cells over time despite the continuous presence of M1 macrophages, which was confirmed by IHC with the M1 macrophage markers iNOS and TNF-α." (PMID 36413402, 2023). "In addition, ADAM17 through TNF/TNFR1 signaling is crucial for tumor cell–induced endothelial cell necroptosis and vascular permeability, which facilitates tumor cell extravasation and metastasis." (PMID 36720499, 2023). "TNF-α has a synergistic effect with chemotherapy and radiotherapy resulting in tumor lysis." (PMID 37370843, 2023). "Multiple in vitro studies have demonstrated that the process of epithelial-to-mesenchymal transition (EMT), a pivotal step for cancer progression with tumor invasion and distant metastasis, is activated by proinflammatory cytokines including TNFα, IL-6, IL-8, and IL-1β." (PMID 37628724, 2023). "Notably, both cIAP and WEE1 inhibitor drug classes are modulators of the TNFα-NFκB pathway, which regulates proliferation, cell death, and tumor promoting inflammation in HNSCC." (PMID 36831373, 2023). "Activated Trm can identify the tumor-associated antigens and secrete cytotoxic granular proteins, CCL3, CCL4, CCL5 and other chemokines, as well as pro-inflammatory cytokines such as interferon-γ (IFN-γ) and tumor necrosis factors (TNF)." (PMID 36969190, 2023). "Tumor necrosis factor (TNF) is involved in regulating the cell cycle of tumor cells." (PMID 37609372, 2023). "This may be due to the overexpression of TNF-α in tumor tissues of DLBC patients and the higher protein level of TNF-α in sera of DLBC patients." (PMID 37428723, 2023). "Moreover, IL-37 reduces tumor promoting cytokines including IL-6, IL-1β and TNF-α produced by both tumor cells and immune cells." (PMID 37928545, 2023).
tumor (continued). "COMT also interacts with the pro-inflammatory cytokine tumor necrosis factor and with the tumor growth factor β1 (TGFβ1) that can modulate expression/activation of other growth factors, such as interferon gamma and tumor necrosis factor alpha, and is frequently up-regulated in tumor cells." (PMID 36827167, 2023). "A study in a murine model demonstrated that neutrophils may be helpful in tumor elimination and metastasis reduction from the combined actions of TNF-α, CD40 agonist, and tumor-binding antibody." (PMID 37631922, 2023). "Evidence has shown that after stimulation by tumor cells, the amount of proinflammatory cytokines, such as tumor necrosis factor (TNF)-α, IFN-γ, and IL-2, released by CIK cells were significantly increased, and these cytokines potentiate systemic antitumor activity." (PMID 37569852, 2023). "Besides IFN-γ, TNF-α, perforin, and Granzyme B production were elevated upon treatment of PD-L1-expressing tumor cells and primary T cells with pentamidine." (PMID 37205112, 2023). "In addition, we found increased frequency of IFNγ– and TNFα-producing CD8+ T cells in the tumor, indicative of their cytotoxic functionality." (PMID 37089449, 2023). "TILT-123 is an ADV with two potent anti-tumor cytokines (TNF-α and IL-2)." (PMID 36604694, 2023). "Furthermore, CD4+ T cells have been shown to modulate tumor metabolism, leading to increased TNF-α-dependent oxidative stress and subsequent tumor cell death." (PMID 37686677, 2023). "Besides the direct anti-tumor effects discussed in the previous paragraph, MC-derived TNFα is also important for T cell activation." (PMID 37376140, 2023). "Notably, Wee1 inhibition leads to increased eradication of tumor cells by cytotoxic T-lymphocyte through tumor necrosis factor (TNF)-α-dependent cell death in several cancer cells." (PMID 37296592, 2023). "Furthermore, the induction of inflammatory cytokines, such as TNF-α and IL-1β, upregulates the expression of selectin on endothelial cells, allowing for enhanced extravasation of T cells into the tumour." (PMID 37627206, 2023). "More defective IFN-γ and TNF-α were produced by intra-tumoral NK cells than non-tumor NK cells." (PMID 38090482, 2023). "This was corroborated by a study that utilized aerobic training, which not only attenuated muscle wasting but also decreased tumor volume, mitigating levels of inflammatory markers such as the IL-10 and TNF-α ratio, along with IL-15 expression in skeletal muscle, in 4T1 cachectic breast cancer mice." (PMID 37755304, 2023). "Endogenous TNF-α may act as a tumor promoter that activates the AP-1 and NF-κB signaling pathways, which stimulate cell proliferation and survival." (PMID 37894821, 2023). "Moreover, the enhanced expression of MHC II and CD80, along with the production of anti-tumor cytokines, such as IL-12 and TNF-α, was observed in the TME." (PMID 37345111, 2023). "Besides, the bubble plots displayed that the ligand–receptor pairs between the epithelial cells and the stromal cells are stronger in the interface and the tumor zones than that in the normal zone including TNF, HLA, collagen and their receptor families." (PMID 37644609, 2023). "The interaction between PD-L1 expressed in tumor cells and PD-1 expressed in T cells inhibits the activity of effector T cells and increases the secretion of proinflammatory cytokines, such as tumor necrosis factor (TNF)-alpha, interleukin (IL)-2, and interferon-gamma (IFN-γ)." (PMID 36674491, 2023). "Therefore, an in-depth exploration of the role of TNF-α in the tumor microenvironment and its mechanisms will be helpful for the development of future cancer treatment strategies." (PMID 36814921, 2023). "A novel frontier for localized TNFα delivery could also potentially be implemented via the direct injection of TNFα-producing MCs into the tumor." (PMID 37376140, 2023).
tumor (continued). "Even more importantly, we could confirm the ability of T lymphocytes to produce IFNγ and TNFα, cytokines that are essential in the process of recognition and anti-tumor cytotoxic capacity." (PMID 37173879, 2023). "They combined the delivery system with cherry to visualize tumor-expressed TNF-α nb." (PMID 37854883, 2023). "In contrast, the antibody blockade against the immune regulator PD-1 molecule on tumour-associated DCs resulted in the inhibition of NF-κB activation, and release of regulatory cytokines, such as IFN-α, IL-6, IL-8 and TNF-α, and the upregulation of co-stimulatory molecules." (PMID 36980527, 2023). "NF-κB p65 (RelA) and TNFα exhibited increased expression in tumor tissue biopsy samples." (PMID 37892820, 2023). "TNF-α promotes apoptosis in immune cells and favors tumor dissemination." (PMID 36851213, 2023). "Furthermore, immunosuppressive cytokines such as TGF-β1 and IL-10 in tumor tissues were decreased by resveratrol, whereas antitumor cytokines TNF-α and IFN-γ were increased." (PMID 37560476, 2023). "IL-1β, TNFα and iNOS were identified as markers of M1 macrophages that inhibited tumor progression." (PMID 37441589, 2023). "The ability of the NF-κB inhibitor to decrease TNF expression by macrophages and also inhibit downstream signaling in tumor cells may be a potential mechanism by which NF-κB inhibition improves efficacy of ruxolitinib in combination." (PMID 37005447, 2023). "TNF-α is considered to be an effective tumoricidal cytokine because of its capacity to directly induce apoptosis and stimulate the inflammatory response at tumor sites." (PMID 37483629, 2023). "Additionally, Alistipes and Ruminoccocus were positively correlated with TNF-dependent anti-tumor immune activation in response to immunotherapy." (PMID 37190186, 2023). "Notably, tumor immune‐related cytokines, including tumor necrosis factor (TNF)‐α, IL‐1β, IL‐2, IL‐6, IL‐17, CD4+/CD8+, IFN‐α, and IFN‐γ, were determined." (PMID 36951443, 2023). "Inflammatory cytokines such as TNFα and IL-1β produced by tumor cells may promote MMP expression in stromal and epithelial cells." (PMID 36677584, 2023). "Animal model research further supports TNF-α’s role in promoting tumor growth and malignancy." (PMID 38022654, 2023). "In the lung tumors from VC-induced mice, the percentage of CD8+ tumor-infiltrating lymphocytes (TILs) was significantly increased upon PV-1 treatment, and the production of granzyme B, TNF-α and IFN-γ by CD8+ cells were all significantly increased in these mice." (PMID 38077406, 2023). "Moreover, both CD3+/CD8+ CTLs and CD3+/CD56+ NKT cells killed tumor cells in cell contact-dependent and -independent manners via granzyme B and interferon-γ/TNF-α, respectively." (PMID 37100864, 2023). "Increased TNF-α in the OSCC tumour microenvironment has been demonstrated to favour invasion through promotion of firstly the pro-inflammatory, pro-invasive phenotypes of OSCC cells and secondly its paracrine mechanism mediating recruitment and activation of inflammatory cells." (PMID 36980727, 2023). "Furthermore, TNF enhances the cytotoxic activity of immune effector cells, such as macrophages and NK cells, against tumor cells (Müller and Kontermann, 2010)." (PMID 38259287, 2023). "Although the exact role of eosinophils in cancer is not fully understood, some studies suggest they contribute towards anti-tumor immunity by inducing tumor death via the production of anti-tumor factors such as TNF-α, along with recruiting CD8+ T cells into tumors via CXCL9 and CXCL10 release." (PMID 38137547, 2023).
tumor (continued). "TGF-β in tumour microenvironment may limit the synthesis of pro-inflammatory immune factors such as TNF-α, IFN-γ and IL-12, while promoting the release of anti-inflammatory factors such as IL-10." (PMID 37162544, 2023). "It is known that the inhibitory effect of M1 macrophages on tumor growth may be enhanced by the production of TNF-α, ROS, and nitric oxide." (PMID 38001420, 2023). "OV-induced tumor immunity can be enhanced by the delivery of anti-tumor cytokines, such as IFNα, TNFα, IL-2, IL-12, and GM-CSF, while tumor-targeted cytokine delivery avoids the significant toxicity associated with systemic delivery while also boosting the immune response." (PMID 38203382, 2023). "Moreover, in human MSCs-treated hepatocellular tissues, TNF-α, IL-6, and α5 integrin expression were elevated to promote tumor growth and metastasis in HCC." (PMID 38022534, 2023). "Recent single-cell transcriptome sequencing studies on HCC have confirmed that different immune cells express different PANoptosis-related genes (CRADD is upregulated in tumor-specific infiltrating regulatory T cells; TNF is upregulated in cytotoxic FGFBP2+ double‐positive T cells)." (PMID 37662906, 2023). "TNF- α is a kind of inflammatory cytokine with strong anti-tumor effect." (PMID 37006260, 2023). "Finally, the signature regulated pathways were involved in TNF signaling, which constitutes a potent immune escape mechanism in the context of a T-cell-inflamed tumor microenvironment, conferring resistance to anti-PD-1." (PMID 37175874, 2023). "Chemo‐drugs may activate caspase 3, triggering pyroptosis via the cleavage of GSDME16 Tumor necrosis factor‐alpha (TNF‐α) activates caspase 8 in tumor cells to activate pyroptosis." (PMID 37752941, 2023). "Moreover, CD8+ T cells in TRIM21-deficient tumours expressed higher levels of IFN-γ and TNF after stimulation with phorbol 12-myristate 13-acetate (PMA) and ionomycin." (PMID 36797289, 2023). "Additionally, pantoprazole displays increased anti‐tumour activity with an augmented expression of anti‐tumour molecules, such as IL‐1, TNF‐α, IL‐2R and NO." (PMID 35961680, 2023). "Previous studies have shown that TNF is involved in the malignant progression of tumors; for example, before tumor cell inoculation, stimulating tumor cells with recombinant TNF and transducing tumor cells with TNF enhanced the metastatic potential of tumor cells in vivo." (PMID 37534250, 2023). "Moreover, tumor angiogenesis was completely abrogated by a TNFα-neutralizing antibody, indicating that TNFα promotes tumor angiogenesis." (PMID 37628724, 2023). "TNF+ Tregs significantly contribute to tumor growth and progression." (PMID 37534250, 2023). "In addition, M1 TAMs enhanced the immune clearance of tumour cells via boosting the performance of CD8+ T cells by increasing the secretions of TNF‐α in GC." (PMID 37608500, 2023). "The activation of the humoral immune system and the secretion of tumor cell-derived cytokines, such as tumor necrosis factor-alpha (TNF alpha), interferon-γ (IFN-γ), interleukin-1β (IL-1β), and interleukin-6 (IL-6) are part of the pathophysiology of cancer-related cachexia." (PMID 38067294, 2023). "The same inhibitory effect could also be seen in TNF-α-activated fibroblasts treated with zerumbone, in which tumor-promoting cytokines TNF-α, TGF-β, IL-33, SDF-1, and MCP-1 were significantly reduced in comparison to TNF-α-activated fibroblasts." (PMID 36986550, 2023). "In the early stage of tumor development, M1 macrophages in tumor tissues express high levels of pro-inflammatory cytokines (such as IFN-γ and TNF-α), directly kill cancer cells, and have the ability to activate the adaptive immune system, which makes M1 macrophages very important in tumor therapy." (PMID 37484024, 2023).
tumor (continued). "Analyzing the subsets of these factors highly expressed by PV001-DV’s infection of PBMCs, several of the known tumor apoptosis-inducing factors such as TNF-a, IL-12p70, are observed to overcome tumor evasion mechanisms, and IL-2 is observed to be synergistic with anti-CTLA-4 therapy." (PMID 37468934, 2023). "In addition, MCs actively participate in tumor cell clearance and tumor rejection through the release of IL-1, IL-4, IL-6, and TNF-α." (PMID 37275909, 2023). "Indeed, TNF-α is a complex cytokine and has been shown to elicit both antitumor and pro-tumor activities depending on tumor-intrinsic characteristics." (PMID 37092550, 2023). "Furthermore, under stimulation by tumor-derived TNF and IL-1, CAFs can produce thymic stromal lymphopoietin (TSLP), which promotes Th2 cell polarization through myeloid DC training." (PMID 37723510, 2023). "TNFα is a cytokine that was initially identified to be responsible for tumor necrosis." (PMID 36996146, 2023). "Interestingly, there has been preclinical evidence that TNF-α blockade can promote tumor regression and enhance ICI-mediated T cell activation against the cancer cells." (PMID 37958355, 2023). "Interferon-γ producing Th1 cells secrete TNF, resulting in tumor destruction." (PMID 36759775, 2023). "In addition, we found that the tumor edge demonstrated increased pro-inflammatory and gliomagenic cytokines including TNF-α, IL-1β, and IL-6." (PMID 37752585, 2023). "In our research, the avirulent ME49Δgra5 tachyzoites could prominently induce the production of the pro-inflammatory cytokines, such as IFN-γ, IL12, and TNF-α, which are key cytokines against tumor development." (PMID 37426671, 2023). "Tumor rechallenge significantly stimulated CD4+ T cells expression of TNFα." (PMID 37407600, 2023). "Considering that neutrophils can recruit macrophages via secreting IL–8 and TNF–α in an inflammatory environment and macrophages can in turn regulate neutrophils function, the TAMs and TANs may have close interrelationships during tumor progression." (PMID 36845095, 2023). "Additionally, NK cells can cause tumor cell death by a direct effect of cytokines such as IFN-γ and TNF-α." (PMID 36769513, 2023). "Anti-TNFα mAb may inhibit tumor progression by suppressing cell proliferation, enhancing immunity against tumors, increasing apoptosis, and suppressing stromal reaction and angiogenesis." (PMID 36996146, 2023). "We next tested whether CX3CL1 will induce these soluble mediators in the presence of IFN-γ, and TNF-α since these inflammatory mediators are likely to be present in the tumor microenvironment and could potentially reduce CX3CL1 induced signals." (PMID 37771579, 2023). "Altogether our findings suggest that the presence of SCF and IL-33 in CRC tissues favor the accumulation of a connective tissue-like MC phenotype which through the production of IL-6 and TNF-α contribute to the establishment of an inflammatory tumor microenvironment." (PMID 37730723, 2023). "In EST-bearing mice, tumor TNF-α revealed marked increments." (PMID 36986504, 2023). "Decreased tumor weight.Increased secretion of TNF-α, IFN-γ, and IL-2.Decreased secretion of IL-4." (PMID 38136228, 2023). "Chemotherapy drugs, the nature of the tumor itself, and the patient’s long-term physiological and psychological stress can lead to an increase in the production of inflammatory cytokines such as TNF-α, IL-1, and IL-6." (PMID 37375330, 2023). "TNF-α and IL-1 secreted by macrophages are strong stimulators of IL-6 produced by tumor cells." (PMID 37151385, 2023). "Furthermore, they found an increase in B cells and cytotoxic T cells to eliminate tumor cells by secreting cytokines such as TNF and IFNγ." (PMID 37408277, 2023). "CRS is a well-recognized adverse effect of CAR-T therapy due to the expansion of CAR T cells and tumor cell apoptosis followed by an inflammatory response consisting of supraphysiological levels of interluekin-6, tumor necrosis factor (TNF), and activated T cells." (PMID 37509525, 2023).